DPY30 (dpy-30 histone methyltransferase complex regulatory subunit)
Diseases named in the same sentence as DPY30 in open-access papers:
DPY30 is named in the same sentence as 28 diseases in open-access papers, as found by Europe PMC text mining. Sharing a sentence is not in itself a finding about the gene and the disease. The quoted sentences say what the papers report.
colorectal cancer (4 papers, 2020 to 2025). A primary or metastatic malignant neoplasm that affects the colon or rectum. "DPY30 has been implicated in tumor-associated inflammation and showed correlations with tumor grade and immune-related gene activation in colorectal cancer, as well as immune cell infiltration in esophageal cancer." (PMID 41357518, 2025). "This study provides compelling evidence that DPY30 is significantly overexpressed in colorectal cancer tissues, with higher expression levels observed in cases with lymph node metastasis compared with those without lymph node metastasis." (PMID 38115111, 2023). "Here, we interrogated the functional role of DPY30 in colorectal cancer cells proliferation in vitro and in vivo." (PMID 37324189, 2023). "Taken together, high expression levels of DPY30 may serve as a novel molecular marker for colorectal cancer." (PMID 37324189, 2023). "Thus, DPY30 may serve as a potential target for colorectal carcinoma." (PMID 37324189, 2023). "Therefore, DPY30 could be a promising target in the treatment of human colorectal carcinoma." (PMID 37324189, 2023).
colon cancer (2 papers, 2018 to 2024). "WDR5, RBBP5, and DPY30 are increased in tumors relative to normal tissue; however, WDR5 is expressed at the highest level and shows the most dramatic increase in expression between normal tissue and colon tumor tissue so it was selected for further study." (PMID 29925347, 2018).
epithelial ovarian cancer (2 papers, 2022 to 2025). "DPY30 is suggested as an oncogene for ovarian cancer and high expression of DPY30 is associated with reduced survival in patients." (PMID 35406529, 2022).
gastric cancer (2 papers, 2015 to 2017). A primary or metastatic malignant neoplasm involving the stomach. "More studies are required to reveal the mechanisms underlying the roles of DPY30 in gastric cancer cells." (PMID 26147337, 2015). "What are molecular mechanisms underlying roles of DPY30 in gastric cancer?" (PMID 26147337, 2015). "In the present study, we showed that components of WRAD (WDR5, RBBP5 and ASH2L) can inhibit proliferation of gastric cancer cells, suggesting that DPY30 act through the increased H3K4MT activity." (PMID 26147337, 2015). "To investigate DPY30 expression in human gastric cancer, we performed immunohistochemistry using a gastric cancer tissue array or archival paraffin-embedded tissue sections." (PMID 26147337, 2015). "In order to determine possible roles of DPY30 in gastric cancer cells, we first knocked-down DPY30 using the ORF-targeting DPY30 siRNA and monitored its knockdown efficiency by real-time PCR." (PMID 26147337, 2015). "Immunohistochemistry and real time PCR showed up-regulation of DPY30 expression in some gastric cancer cell lines and patients’ tissues." (PMID 26147337, 2015). "However, recently the upregulation of DPY30 expression in gastric cancer cell lines and patients' tissues has been reported." (PMID 28160335, 2017). "In this study, to determine whether DPY30 has pathophysiological roles in gastric cancer, its expression and roles were examined." (PMID 26147337, 2015). "In the present study, we showed novel roles of DPY30 in gastric cancer." (PMID 26147337, 2015). "We also checked mRNA levels of DPY30 in gastric cancer tissues." (PMID 26147337, 2015). "In the present study, we showed roles of DPY30 as an oncoprotein in the gastric cancer." (PMID 26147337, 2015). "We next examined whether DPY30 regulates the migration of gastric cancer cells." (PMID 26147337, 2015). "Notably, DPY30 was overexpressed in invading gastric cancer cells." (PMID 26147337, 2015). "Up-regulation of DPY30 expression was observed only in SNU1 and SNU16 gastric cancer cells among six gastric cancer cells we have examined." (PMID 26147337, 2015). "Furthermore, we determined mRNA levels of DPY30 in one immortalized normal gastric epithelial cell line (HFE145) and six gastric cancer-derived cell lines (SNU1, SNU16, SNU216, SNU620, SNU638 and NCI-N87) using real-time PCR." (PMID 26147337, 2015). "DPY30 is amplified (data not shown) and highly expressed in some gastric cancer tissues." (PMID 26147337, 2015).
leukaemia (2 papers, 2021 to 2025). "Besides its role in facilitating H3K4 methylation through the KMT2A complex, DPY30 itself regulates the differentiation and proliferation of haematopoietic stem cells and progenitor cells, and it promotes cell growth in leukaemia cells induced by KMT2A fusion genes." (PMID 39888275, 2025).
Burkitt lymphoma (1 paper, 2020). A rare form of malignant mature B-cell non-Hodgkin lymphoma. "Studies on Burkitt’s lymphoma have shown that DPY30, like other KMT2 core subunits, is upregulated by the MYC oncoprotein and is significant for the binding of MYC to its target genes; thus, it plays an important role in MYC-driven tumorigenesis." (PMID 33302406, 2020). "DPY30 was found to be upregulated in Burkitt’s lymphoma, and its downregulation can have a negative effect on cell transformation dependent on MYC activity." (PMID 33302406, 2020).
cervical squamous cell carcinoma (1 paper, 2023). A squamous cell carcinoma arising from the cervical epithelium. "It has been found that the expression level of DPY30 can affect the EMT process in cervical squamous cell carcinoma." (PMID 38115111, 2023). "For example, the previous study about DPY30 regulating cervical squamous cell carcinoma by mediating EMT, and DPY30 is required for the enhanced proliferation, motility and EMT of epithelial ovarian cancer cells." (PMID 38115111, 2023).
co-infection (1 paper, 2015). "Such co-infection, however, did not increase the effect on Dpy30 and Wdr5 expression." (PMID 26691508, 2015).
colitis (1 paper, 2023). Inflammation of the colon. "the expression of DPY30 gradually increases in the continuous progression of CRC from colitis to colitis-associated CRC tumor." (PMID 37324189, 2023).
diabetes (1 paper, 2023). "Dpy30-KO mice developed impaired glucose tolerance and had reduced serum insulin levels by 45 days post tamoxifen administration and then rapidly developed diabetes, prompting euthanasia by 60 days." (PMID 36912927, 2023). "Beta cell function, gene expression and chromatin modifications were analysed in conditional Dpy30 knockout mice, in which H3K4 methyltransferase activity is impaired, and in a mouse model of diabetes." (PMID 36912927, 2023).
hereditary spastic paraplegia (1 paper, 2018). Hereditary spastic paraplegias (HSP) comprise a genetically and clinically heterogeneous group of neurodegenerative disorders characterized by progressive spasticity and hyperreflexia of the lower limbs. "Here we report a novel epistatic interaction between SPAST and the contiguous gene DPY30, which modifies age at onset in hereditary spastic paraplegia, a genetic axonopathy." (PMID 29481671, 2018).
hyperglycaemia (1 paper, 2023). "Deletion of Dpy30 from maturing beta cells using Ins1Cre caused reduction of H3K4 methylation in islets by 5 weeks of age, leading to hyperglycaemia, impaired glucose tolerance and reduced serum insulin levels." (PMID 36912927, 2023).
Infertility (1 paper, 2014). "As it orthologue, it can be speculated that human DPY30 is also implicated in brain development and infertility and when mutated might lead to miscarriages." (PMID 24690193, 2014).
intestinal tumours (1 paper, 2021). "Additionally, the histopathological analysis showed that DPY30 expression levels were substantially higher in intestinal tumours from ApcMin/+/Abhd5f/f/Cre+ mice than in those from control ApcMin/+Abhd5+/+/Cre+ mice." (PMID 34795238, 2021). "In addition, AAV-induced Dpy30 silencing in ApcMin/+/Abhd5f/f/Cre+ mice abolished the increases in YAP methylation and c-Met levels in intestinal tumours and significantly inhibited tumour formation and malignant transformation." (PMID 34795238, 2021).
lung carcinoma (1 paper, 2025). "MiR-614 was found to inhibit cell proliferation, CHD4 regulates both proliferative and migratory abilities of NSCLC cells via the RhoA/ROCK pathway, while the role of DPY30 has not yet been clarified in lung cancer." (PMID 40282457, 2025).
pancreatic cancer (1 paper, 2021). "Meanwhile, we also found that the expression of DPY30 in patients with moderately and highly differentiated pancreatic cancer was significantly lower than that in patients with poorly differentiated pancreatic cancer, further confirming that DPY30 accelerated the progression of pancreatic cancer." (PMID 34090418, 2021).
cancer (9 papers, 2015 to 2023). A tumor composed of atypical neoplastic, often pleomorphic cells that invade other tissues. "DPY30 is critically implicated in cancers such as cholangiocarcinoma, MLL-rearranged leukemia, gastric cance r, and epithelial ovarian cancer." (PMID 38115111, 2023). "Our study identified ABHD5 as an upstream factor that regulates DPY30 degradation and nuclear translocation, suggesting the mechanism underlying DPY30 overexpression and activation in cancer pathogenesis." (PMID 34795238, 2021). "Therefore, it is reasonable to speculate that the abnormal regulation of DPY30 will lead to aberrant methylation of histones, which may cause the disturbance of body homeostasis and eventually lead to the occurrence of cancer." (PMID 34090418, 2021). "Further investigations are warranted to explore the interactions between DPY30 and other core subunits in order to elucidate their role in promoting cancer metastasis." (PMID 38115111, 2023). "Extensive studies have reported that DPY30 is overexpressed in many types of cancers, accompanied by increased H3K4me3 modification in cancer cells." (PMID 36065180, 2022). "Considering the importance of DPY30 in development and cancers, our discovery is necessary to explain how DPY30 stably exists in cells." (PMID 35563756, 2022). "We found that two risk genes, DPY30 and PADI1, were significantly positively associated with several identified cancer-related genes." (PMID 34090418, 2021). "Although the core subunits of KMT2 complexes such as WDR5, RBBP5, DPY30, and ASH2L are rarely deleted or carry genetic mutations, they are frequently amplified or upregulated in human cancers and act as oncogenes." (PMID 33302406, 2020). "In normal gastric tissues, DPY30 expression was difficult to detect, but in cancer tissues DPY30 protein was widely overexpressed." (PMID 26147337, 2015). "Roles of DPY30 in cancer biology have been poorly characterized although its roles in differentiation of ESCs and hematopoietic progenitor cells had been reported." (PMID 26147337, 2015). "The difference is that the mechanism of DPY30 promoting cancer progression is different." (PMID 38115111, 2023). "Additionally, the tissue-wise expression of DPY30 in different cancer types using The Human Protein Atlas website revealed that DPY30 was the second most highly expressed gene in CRC compared with other cancers." (PMID 38115111, 2023). "Indeed, DPY30 is overexpressed in cancer, and high DPY30 expression levels are correlated with poor prognosis and functionally promote tumourigenesis in certain types of cancer." (PMID 34795238, 2021). "For example, DPY30 was significantly positively correlated with SETD1A, SETDB1 and RBBP5, which have been reported to promote the occurrence and progression of cancers." (PMID 34090418, 2021). "DPY30, like other core subunits of the KMT2 complexes, has been found to be overexpressed in many cancers." (PMID 33302406, 2020). "DPY30, a core subunit of the SET1/MLL histone H3K4 methyltransferase complexes, plays an important role in diverse biological functions through the epigenetic regulation of gene transcription, especially in cancer development." (PMID 37324189, 2023). "The four histone modification-related genes highlighted, including DPY30, CBX8, CENPT, and PADI1, have been reported to have the potential to regulate the occurrence and development of cancer to some extent by altering the histone modification of cancer-related genes." (PMID 34090418, 2021). "Therefore, DPY30 and H3K4 methylation were suggested as potential epigenetic pathways that could be therapeutically targeted in MYC-dependent cancers." (PMID 33302406, 2020).
tumor (7 papers, 2021 to 2025). "The high expression rate of DPY30 in tumor tissues was 58.51% (55/94 cases), which was much higher than in paratumor tissues (8.14%, 7/86 cases)." (PMID 37324189, 2023). "Upon clinicopathological characteristics correlation analysis, elevated DPY30 protein levels positively correlated with pathological grading (P = 0.0348), tumor size (P = 0.0192), TNM stage (P = 0.0365), and tumor location (P = 0.019) in CRC patients." (PMID 37324189, 2023). "As for the correlation of DPY30 with the actual tumor grade/stage, the IHC staining of DPY30 in different CRC TNM grades (AJCC I, II, III and IV) revealed that the expression level of DPY30 was positively correlated with TNM grades." (PMID 37324189, 2023). "elevated DPY30 protein levels positively correlated with clinicopathological characteristics, such as pathological grading, tumor size, TNM stage in CRC patients through tissue microarray." (PMID 38115111, 2023). "Here we demonstrated that DPY30 was overexpressed in CRC tissues, and significantly associated with pathological grading, tumor size, TNM stage, and tumor location." (PMID 37324189, 2023). "We therefore propose that combination therapy with a DPY30 inhibitor and a c-Met inhibitor will have a synergistic effect on tumour suppression." (PMID 34795238, 2021). "This highlights DPY30 as a critical regulator of epigenetic modifications supporting GSC-driven tumor progression and identifies both DPY30 and PDE4B, a downstream target of DPY30, as potential therapeutic targets in GBM, with the PDE4 inhibitor rolipram as a promising agent." (PMID 40565099, 2025). "Moreover, the downregulation of DPY30 was associated with lower expression of PCNA, Ki67, cyclin A and H3K4me3 in DPY30-knockdown xenograft tumor tissues than control group appreciably." (PMID 37324189, 2023). "However, the correlation of DPY30 with tumor metastasis and the mechanism by which it triggers metastasis remain to be elucidated." (PMID 38115111, 2023). "Of the 25 CRC samples, 72% of tumor samples presented DPY30 overexpressed." (PMID 37324189, 2023). "Overexpression of DPY30 promotes proliferation, migration, and invasion of tumor cells." (PMID 36065180, 2022). "Besides, the correlation between DPY30 with tumor metastasis deserves to be elucidated." (PMID 37324189, 2023). "The expression of DPY30, N-Cadherin, and Vimentin were upregulated in the CRC tumor region (bottom right), but the expression level of E-Cadherin in the CRC tumor region (bottom right) was lower than that in para-tissues (upper left)." (PMID 38115111, 2023). "Our results suggest that DPY30 plays a vital role in promoting EMT progression in CRC cells and in facilitating tumor metastasis." (PMID 38115111, 2023). "Among them, DPY30, EREG, PLA2G16, ZNF185, PADI1, INPP4B and AP1S3 have been reported to be involved in tumor genesis and progression, and they were significantly positively correlated with risk score." (PMID 34090418, 2021). "Compared with CBX8 and DPY30, CENPT and PDAI1 have been less reported on promoting tumor development by influencing histone modification." (PMID 34090418, 2021). "Targeting DPY30 selectively inhibited tumor formation in vivo without impairing GSC proliferation in vitro, suggesting its role in reprogramming the H3K4me3 landscape to support angiogenesis and hypoxia-related signaling in the tumor microenvironment (TME)." (PMID 40565099, 2025). "Tissue microarrays were also used to analyze DPY30 expression on 94 CRC tissues and 86 paired paratumor tissues by IHC staining, and demonstrated that DPY30 expression was much higher in the tumor tissue than in paratumor tissue, and mainly localized in the cell nucleus." (PMID 37324189, 2023). "In this study, we found DPY30 was overexpressed in CRC cells and CRC tissues, moreover, its expression was appreciably increased with CRC development, correlated with pathological grading, tumor size, TNM stage, and tumor location." (PMID 37324189, 2023).
tumor (continued). "In accordance with these findings, DPY30 silencing in ABHD5-knockdown HCT116 cells significantly decreased self-renewal and AI growth in vitro and inhibited xenograft tumour growth and metastasis in vivo." (PMID 34795238, 2021). "Analysis of the correlation scatter plot of the IHC score showed DPY30 protein level was positively correlated with PCNA (R = 0.6954, P = 0.0040), Ki67 (R = 0.6691, P < 0.0064) and cyclin A (R = 0.7474, P < 0.0014) in subcutaneous xenograft tumor tissues, respectively." (PMID 37324189, 2023).
DPY30 also shares sentences with these, for which no sentence is quoted: colon adenocarcinoma (2 papers); congenital heart defects (1); esophageal cancer (1); Impaired glucose tolerance (1); lymph node metastasis (1); Miscarriage (1); neurodegenerative disease (1); ovarian cancer (1); rectal adenocarcinoma (1); Spastic paraplegia (1).